CFTR (CF transmembrane conductance regulator)
Diseases named in the same sentence as CFTR in open-access papers (continued):
Sharing a sentence is not in itself a finding about the gene and the disease.
leukemia (3 papers, 2017 to 2020). A malignant (clonal) hematologic disorder, involving hematopoietic stem cells and characterized by the presence of primitive or atypical myeloid or lymphoid cells in the bone marrow and the blood. "HDAC2 is implicated in epigenetics and have been shown to be associated to CFTR expression for PTEN-pathway regulation in Ph+ leukemia cell lines." (PMID 32517078, 2020). "Despite recent interest in the correlation between abnormal CFTR protein (including expression and mutations) and various cancers, studies of the role of CFTR in cancer pathogenesis, particularly leukemia, remain limited." (PMID 28445932, 2017). "We assessed the cell apoptosis and cell cycle distribution of CFTR-high leukemia cell lines and corresponding primary leukemia cells by flow cytometry after treatment with CFTRinh-172." (PMID 28445932, 2017). "Because the CFTR inhibitor showed a strong anti-leukemia effect, we sought to determine the effect of down-regulating CFTR expression on BCR-ABL and classic Wnt/β-catenin signaling." (PMID 28445932, 2017). "To evaluate the role of CFTR in leukemia cells, we investigated the expression of CFTR protein in normal cells and leukemia cells, including seven common leukemia cell lines and 138 primary acute leukemia samples, by Western blotting assay." (PMID 28445932, 2017). "We further demonstrated that high concentrations of CFTRinh-172 (100–200 μM) resulted in significant anti-proliferative, apoptotic and cell cycle-arrest effects in CFTR-high leukemia cells but had little effect on normal cells." (PMID 28445932, 2017). "Related studies have been limited to investigating the expression and function of the CFTR ion channel in leukemia cells but have rarely delved into survival-related functions and mechanisms, especially regarding its interaction with other proteins." (PMID 28445932, 2017). "It was therefore crucial to investigate the role of CFTR in the survival of leukemia cells." (PMID 28445932, 2017). "In addition, CFTR will be the focus of future research into other types of leukemia and lymphoma." (PMID 28445932, 2017). "CFTR protein is abnormally expressed in several types of tumor cells that originated as epithelial cells, but its role inhuman leukemia had not previously been described." (PMID 28445932, 2017). "Unexpectedly, we found that CFTR protein was located in the cytosol in leukemia cells and normal MNCs." (PMID 28445932, 2017). "Importantly, not all of the leukemia cells expressed elevated CFTR protein; CFTR expression in a small fraction of leukemia cells was similar to that observed for normal cells." (PMID 28445932, 2017).
liver cancer (3 papers, 2020 to 2023). An epithelial or non-epithelial malignant neoplasm that arises from the liver. "Studies have identified associations between CFTR-related genetic variations and increased susceptibility to liver cancer in CF patients." (PMID 37686519, 2023). "In addition to CFTR mutations, other CF-related genetic factors have been associated with an increased risk of hepatic cancer." (PMID 37686519, 2023). "In summary, there has been growing evidence supporting a link between CF, CFTR dysfunction, and the development of hepatic cancer." (PMID 37686519, 2023). "In liver cancer PROM1 was more strongly co-expressed with a larger number of genes, including CFTR, KRT7, ANXA3, TACSTD2, and FZD1." (PMID 31164716, 2020).
myocardial ischemia (3 papers, 2013 to 2026). A disorder of cardiac function caused by insufficient blood flow to the muscle tissue of the heart. "The results of the current study show that the myocardial ischemia of rats may be caused by an increased concentration of protein CFTR and CLC-2 after activating chloride channel of myocardial tissue." (PMID 23864885, 2013). "The results of the study implies that acupuncture suppresses the pathological changes of cardiac tissue of rats with myocardial ischemia and regulates the protein expression of CFTR and CLC-2 CL− channels, which may serve as one possible mechanism to reduce myocardial ischemia." (PMID 23864885, 2013). "The results show that acupuncture can alleviate the myocardial ischemia of cardiac tissue, decrease significantly the activities of serum SOD and MDA, and thereby influence the protein expressions of CFTR and CLC-2 in CL− channels." (PMID 23864885, 2013). "In this study, the impact of acupuncture on the protein expressions of Cystic Fibrosis Transmembrane Conductance Regulator (CFTR) and CLC-2 CL− channel of the rats with myocardial ischemia were tested and its mechanism was explored." (PMID 23864885, 2013). "Blocking of CL− channel by acupuncture at Neiguan (PC-6) can reduce the concentration of protein CFTR and CLC-2, which could be one mechanism to treat rat myocardial ischemia." (PMID 23864885, 2013).
nephrogenic diabetes insipidus (3 papers, 2012 to 2021). Nephrogenic diabetes insipidus (NDI) is characterized by polyuria with polydipsia, recurrent bouts of fever, constipation, and acute hypernatremic dehydration after birth that may cause neurological sequelae. "These substances have been shown to successfully rescue trafficking of mutant CFTR in vitro or to cause improved maturation of vasopressin V2 receptor mutants involved in nephrogenic diabetes insipidus." (PMID 22973456, 2012).
oesophageal adenocarcinoma (3 papers, 2016 to 2022). "Considering the second panel the top central DEGs is CFTR that has been previously reported to have some associations with BE and oesophageal adenocarcinoma." (PMID 30774811, 2018).
Opportunistic infection (3 papers, 2010 to 2025). An infection that is caused by a pathogen that would generally not be able to cause an infection in a host with a normal immune system. "Specifically, one study with HDAd encoding CFTR under K18 control delivered to CFTR-/- mice lung, showed the correct localization of the CFTR protein in the appropriate target cell types and the protection of the lungs from opportunistic infections." (PMID 21994713, 2010).
primary immunodeficiencies (3 papers, 2023 to 2025). "Different heterozygous mutations affecting the cystic fibrosis transmembrane conductance regulator (CFTR) also exacerbate the lung injuries in primary immunodeficiencies." (PMID 39596040, 2024). "Importantly, no mutations related to primary immunodeficiency disease or cystic fibrosis transmembrane conductance regulator (CFTR)-related disorders were identified in these subjects." (PMID 40065384, 2025).
primary sclerosing cholangitis (3 papers, 2016 to 2021). "Additionally, non-CF-causing CFTR mutations have been associated with primary sclerosing cholangitis in some patients, further supporting the role of CFTR in these diseases." (PMID 27382190, 2016).
Recurrent pancreatitis (3 papers, 2010 to 2021). A recurrent form of pancreatitis. "CFTR mutations were originally identified in patients with cystic fibrosis, but later they were also found to be associated with male vas deference infertility and chronic or recurrent pancreatitis." (PMID 33682322, 2021).
renal fibrosis (3 papers, 2017 to 2022). A final common manifestation of a wide variety of chronic kidney diseases characterized by glomerulosclerosis and tubulointerstitial fibrosis. "Recent evidence shows that CFTR inhibits UUO-induced renal fibrosis by affecting Wnt/β-catenin signaling." (PMID 33621200, 2021). "As a result, disruption of the interaction due to loss of CFTR results in aberrant activation of the Wnt/β-catenin-dependent EMT, leading to renal fibrosis." (PMID 28701694, 2017). "CFTR inhibits UUO-induced renal fibrosis by interfering with β-catenin activation." (PMID 33621200, 2021). "Taken together, these data imply that CFTR downregulation during renal fibrosis is not related to TGF-β signaling." (PMID 28701694, 2017).
sarcopenia (3 papers, 2023 to 2025). Progressive decline in muscle mass due to aging which results in decreased functional capacity of muscles. "Promising data achieved presently by local administration of either CFTR‐containing virus or VX809 in aged wild‐type mice have confirmed the potential of enhancing CFTR as a new therapeutic strategy for sarcopenia or other skeletal muscle disorders in a general population." (PMID 39887939, 2025).
urea cycle disorder (3 papers, 2010 to 2024). A genetic inborn error of metabolism characterized by the deficiency of one of the enzymes necessary for the urea cycle. "Sodium 4-phenylbutyrate (PBA), an otherwise approved drug for urea cycle disorders, proved to be a clinically relevant chemical chaperone restoring chloride transport of the mutated ΔF508 Cystic Fibrosis Transmembrane Conductance Regulator (CFTR)." (PMID 32660097, 2020). "FDA-approved for the treatment of urea cycle disorders in children, 4-PBA has shown promise in reducing ER retention, preventing misfolding and ameliorating mislocalisation of CFTR mutants both in vitro and in vivo." (PMID 38674104, 2024). "Small molecular chaperones were originally developed to promote cystic fibrosis transmembrane conductance regulator (CFTR) trafficking, and one member of the family, phenylbutyric acid (PBA) is already FDA approved for treatment of urea cycle disorder." (PMID 20161760, 2010).
urolithiasis (3 papers, 2022 to 2025). Stone(s) within the urinary tract. "Recent studies have shown that patients receiving Trikafta, a CFTR modulator, exhibited significantly reduced urinary magnesium levels, which is a known risk factor for urolithiasis." (PMID 41244782, 2025).
acute lymphoblastic leukemia (2 papers, 2017 to 2021). Leukemia with an acute onset, characterized by the presence of lymphoblasts in the bone marrow and the peripheral blood. "The aberrant expression and mutation of CFTR have been observed in several tumor, but not in philadelphia chromosome–positive(Ph+) acute leukemia, including Ph+ B cell acute lymphoblastic leukemia(Ph+ B-ALL) and chronic myelogenous leukemia blast crisis phases (CML-BC)." (PMID 28445932, 2017).
airway hyperresponsiveness (2 papers, 2023 to 2024). "Together, our study reveals that PM2.5 impairs the ATP-induced transepithelial anion Isc through downregulating P2Y2R/CFTR pathway, and this process may participate in aggravating airway hyperresponsiveness and airway inflammation." (PMID 39113893, 2024). "Therefore, CFTR plays an important role in maintaining the homeostasis of bronchial epithelium and lowering the airways hyperresponsiveness and dysfunction." (PMID 36226596, 2023). "Furthermore, PM2.5 exposure reduced the ATP-induced epithelial anion short-circuit current by downregulating P2Y2R/CFTR pathway in vitro and in vivo, and this process may participate in aggravating airway hyperresponsiveness and airway inflammation." (PMID 39113893, 2024). "In summary, this study demonstrated that PM2.5 exposure impaired airway epithelial barriers through inhibiting ATP-induced anion Isc by downregulating P2Y2R/CFTR pathway, and this process may participate in worsening airway hyperresponsiveness and airway inflammation." (PMID 39113893, 2024).
alcoholic pancreatitis (2 papers, 2009 to 2023). Acute or chronic inflammation of the pancreas due to excessive alcohol drinking. "Similarly, ethanol induces mutations in CFTR that render alcoholic pancreatitis more severe." (PMID 36835437, 2023). "Mutations of CFTR may also play a role in the development of alcoholic pancreatitis." (PMID 20049222, 2009). "The generation of an organoid model in which CFTR damage induces a chain of events in response to calcium overload has demonstrated an increase in calcium excretion as a new therapeutic direction for alcoholic pancreatitis." (PMID 36835437, 2023). "However, studies of the fibrogenesis and genetic modifications of alcoholic pancreatitis have improved our knowledge of this disease, demonstrating that SPIN-1 and CFTR gene modification may act as modifier genes." (PMID 20049222, 2009).
Alkalosis (2 papers, 2020). Depletion of acid or accumulation base in the body fluids. "There could be an association between alkalosis and rare CFTR mutations such as S737F, which has already been shown to be associated with salt-loss syndrome at diagnosis." (PMID 32630227, 2020).
allergic disease (2 papers, 2021 to 2025). An immune response that occurs following re-exposure to an innocuous antigen, and that requires the presence of existing antibodies against that antigen. "Limitations include the following: (a) We cannot exclude the possibility of CFTR effects on other cell types of the innate and adaptive immune system in our allergy model." (PMID 40131363, 2025). "(d) Using a recently developed humanized CFTR mouse model, we demonstrated an in vivo ivacaftor-mediated decrease in allergy through reductions in type 2 cytokines (IL-5 and IL-13) and total serum IgE." (PMID 40131363, 2025). "The recently approved CFTR potentiator, ivacaftor, decreased inflammation in an in vivo mouse allergy model and reduced GATA3 expression and effector function in in vitro polarized human Th2 cells." (PMID 40131363, 2025). "The ability of CFTR to suppress Th2 responses arising from allergy, both through epithelial-derived cytokines and Th2 cell function, provides a unique opportunity to therapeutically target a novel multicellular immunomodulatory pathway." (PMID 40131363, 2025). "We show that the CFTR potentiator ivacaftor in a mouse model of allergic disease significantly reduced allergic inflammation through reductions in recruited eosinophils and lymphocytes, as well as through production of IgE compared with vehicle treated mice." (PMID 40131363, 2025). "(b) Cre recombinase–driven deletion of T cell–specific CFTR in mice provided a powerful approach to assess CD4+ T cell CFTR function in allergy, a method that would be more challenging in larger-animal CF models." (PMID 40131363, 2025). "CFTR potentiation reduces allergic inflammation, offering therapeutic potential for allergy." (PMID 40131363, 2025). "Taken together, these data demonstrate that CFTR modulation decreased Th2 effector function and suggest that targeting CFTR may represent an adjunct to current therapies in allergic disease." (PMID 40131363, 2025). "CFTR-targeting compounds may serve as potential adjuvants to current allergy therapies by mechanistically targeting nonredundant pathways in allergic disease." (PMID 40131363, 2025). "The goal of this study was to determine whether CFTR negatively regulates CD4+ T cell differentiation and effector function in allergic disease and if strategies to increase CFTR function may provide therapeutic potential in airway inflammation through T cell direct and indirect mechanisms." (PMID 40131363, 2025). "The CFTR modulator drug class may provide pharmacological approaches to managing common and persistent type 2 inflammation in CF via epithelial and CD4+ T cell mechanisms, while more broadly representing a new class of therapies to be repurposed for allergic disease." (PMID 40131363, 2025).
anxiety disorder (2 papers, 2023 to 2025). A category of psychiatric disorders which are characterized by anxious feelings or fear often accompanied by physical symptoms associated with anxiety. "His pre-existing anxiety disorders did not suggest a causal link with the CFTR modulator." (PMID 41226552, 2025).
bacterial pneumonia (2 papers, 2023 to 2025). Acute infection of the lung parenchyma caused by bacteria (e.g., Streptococcus pneumoniae, Haemophilus influenzae, Chlamydia pneumoniae, Mycoplasma pneumoniae, and Legionella pneumophila). "However, it remains unclear the amounts of CFTR modulators that reach the airway lumen and whether bacterial pneumonia can alter their PK profiles." (PMID 36625583, 2023).
Bartter syndrome (2 papers, 2023 to 2025). "Restoring CFTR in secretory cells may be key for CF gene therapy because people with Bartter syndrome — caused by mutations in barttin or ClC-K Cl– channels — do not develop CF airway disease." (PMID 37581935, 2023).
cholelithiasis (2 papers, 2020 to 2022). The presence of crystallized deposits forming in the gallbladder or biliary tree, primarily composed of cholesterol, bilirubin, and bile. "Only one of the seven patients was CFTR modulator naïve prior to ELX/TEZ/IVA, and five of the patients had chronic cholecystitis and cholelithiasis." (PMID 33374882, 2020).
chronic granulomatous disease (2 papers, 2023 to 2025). Chronic granulomatous disease (CGD) is a rare primary immunodeficiency, mainly affecting phagocytes, which is characterized by an increased susceptibility to severe and recurrent bacterial and fungal infections, along with the development of granulomas. "Among the genetic disorders associated with these aspergillosis syndromes, ABPA is primarily seen with CFTR mutations, while IA and CPA are largely seen in chronic granulomatous disease (CGD), autosomal dominant hyper-IgE (Job’s) syndrome, GATA2 deficiency, and CARD9 deficiency." (PMID 36986378, 2023).
colorectal tumor (2 papers, 2020 to 2024). "Increasing evidence demonstrated the close association between inactivating mutations in the CFTR and susceptibility to colorectal tumor development." (PMID 38528462, 2024).
diabetes mellitus type 1 (2 papers, 2017 to 2025). "The goal of this work was to determine if type 1 diabetes induces low expression of megalin, cubilin, ClC‐5, and CFTR in renal tissues and if this fact is associated with the microalbuminuria and LMW proteinuria observed in DN disease." (PMID 28676554, 2017). "The goal of this work was to evaluate renal function and the expression of megalin, cubilin, CFTR (cystic fibrosis transmembrane conductance regulator), and ClC‐5 in the proximal tubule and renal cortex of rats with type 1 diabetes." (PMID 28676554, 2017).
Down syndrome (2 papers, 2017 to 2025). "Despite typical Down syndrome features, elevated sweat chloride and a heterozygous CFTR mutation were identified." (PMID 40241998, 2025).
duodenal ulcer (2 papers, 2018 to 2024). An ulcer in the duodenal wall. "This study clarifies the mechanism whereby H. pylori infection induces duodenal epithelial cellular CFTR and SCL26A6 expression decreases and contributes to further elucidating the pathogenesis of H. pylori-associated duodenal ulcer." (PMID 30119655, 2018). "H. pylori infection downregulates duodenal epithelial cellular CFTR and SLC26A6 expressions through TGFβ-mediated P38 MAPK signaling pathway, which contributes to further elucidating the pathogenesis of H. pylori-associated duodenal ulcer." (PMID 30119655, 2018). "We previously showed that H. pylori infection downregulated the expression and functional activity of duodenal mucosal CFTR and SLC26A6, which contributes to the development of duodenal ulcer." (PMID 30119655, 2018).
edema (2 papers, 2017 to 2024). An abnormal accumulation of fluid beneath the skin, or in one or more cavities of the body. "The basolateral expressed Na+-K+-2Cl− cotransporter 1 (NKCC1) and the apical Cl− channel cystic fibrosis transmembrane conductance regulator (CFTR) are considered to be critically involved in the pathogenesis of pulmonary edema and have also been implicated in the inflammatory response in ARDS." (PMID 28439270, 2017). "Cystic fibrosis transmembrane conductance regulator (CFTR) facilitates the release of Cl- to promote the secretion of uterine fluid; however, its overexpression can lead to the formation of hydrops and hence prevent embryo implantation." (PMID 38785947, 2024). "Although these effects have traditionally been attributed to diuretic effects of non-specific NKCC inhibitors, improvement of respiratory function by furosemide in lung edema precedes the onset of diuresis, suggesting alternative mechanisms such as NKCC/CFTR-mediated AFS in edema formation." (PMID 28439270, 2017).